NRF1 (nuclear respiratory factor 1)
Diseases named in the same sentence as NRF1 in open-access papers (continued):
Sharing a sentence is not in itself a finding about the gene and the disease.
Alzheimer disease (11 papers, 2016 to 2025). A progressive, neurodegenerative disease characterized by loss of function and death of nerve cells in several areas of the brain leading to loss of cognitive function such as memory and language. "Since levels of NRF1 are significantly decreased in both Alzheimer’s disease hippocampal tissues and AD-causing amyloid precursor protein mutant cells, impaired mitochondrial biogenesis is implicated to contribute to mitochondrial dysfunction in Alzheimer’s disease." (PMID 27983596, 2016). "Previous studies have shown that GRIN2B, a target gene of nuclear respiratory factor 1, plays a role in Alzheimer’s disease." (PMID 31611906, 2019). "A recent study has suggested that pharmacological activation of Nrf1 is protective in a mouse model of one age-dependent neurodegenerative condition – spinal and bulbar muscular atrophy, and our data indicates SKN-1A/Nrf1 is similarly protective in a C. elegans model of Alzheimer’s disease." (PMID 30973820, 2019). "NRF1 target genes -PSENEN AND MAPT are involved in Alzheimer’s disease." (PMID 27983596, 2016). "On the other hand, in certain neurodegenerative diseases (e.g., Alzheimer’s disease) that exhibit ubiquitylated protein aggregates in the neurons, there could be interest in enhancing the Nrf1-dependent proteasome and autophagy pathways to clear the aggregates and improve proteostasis." (PMID 38656405, 2024). "Animal studies have also revealed a reduction in the levels of PGC-1α, Nrf1, Nrf2, and TFAM in the brain tissue of triple transgenic Alzheimer’s disease mouse models (3 × Tg-AD)." (PMID 41178992, 2025). "The importance of mitochondrial biogenesis in neurons is also reflected by the observation that PGC-1α, NRF-1 and TFAM are downregulated in several neurodegenerative diseases, such as Huntington’s (HD), Parkinson’s (PD) and Alzheimer’s diseases (AD)." (PMID 34884861, 2021). "In a C. elegans Alzheimer’s disease model, SKN-1A/Nrf1 slows accumulation of the amyloid beta peptide and delays adult-onset cellular dysfunction." (PMID 30973820, 2019).
steatosis (11 papers, 2018 to 2026). Increased lipid within the cytoplasm of cells. "Particularly, deficiency of NRF1 resulted in apoptosis, steatosis and spontaneous development of tumors in the mouse liver." (PMID 41545342, 2026). "A bulk of ubiquitinated and/or oxidative damaged proteins, besides lipids, was also accumulated in the Nrf1-/- hepatocytes, leading to the ER stress-associated steatosis." (PMID 40703332, 2025). "Contrarily, similar ER stress responses and resultant steatosis were enhanced by the half loss of Nrf1 in the heterozygous (Nrf1+/−) livers, when compared with wild-type (Nrf1+/+) livers, in response to 26S proteasomal inhibition." (PMID 31861550, 2019). "Herein, we proposed that NRF1 alleviated the steatosis, liver damage, inflammation and fibrosis of MASH by inhibiting ER stress in hepatocytes." (PMID 41545342, 2026). "Through a gross examination of livers, H&E staining of hepatic tissues and a record of liver weights, we found that the addition of DHA protected the liver against HFD-induced steatosis and liver injury, which was reversed by liver-specific NRF1 knockdown." (PMID 41545342, 2026). "Collectively, the results of this study suggest that EMPA ameliorates MASLD by reducing steatosis and attenuating oxidative stress via NRF1." (PMID 40362294, 2025). "Overall, the results here are consistent with previous studies of the individual role of Nrf1 and Nrf2 on liver steatosis and steatohepatitis using embryonic null mice or transgenic promoter-driven Cre recombinase mice crossed with Nrf1 flox mice." (PMID 39125617, 2024). "Combined induction of Nrf2 via bardoxolone and Nrf1 via hNRF1 expression reduced steatosis, inflammation, proliferation, and fibrosis." (PMID 39125617, 2024). "Furthermore, inhibition of Nrf1 activity correlated with a kinome profile characteristic of steatosis and enhanced inflammation—factors contributing to HCV pathogenesis." (PMID 40872767, 2025). "Induction of hepatic Nrf1 activity with hNRF1 enhanced the effect of bardoxolone on steatosis and may have stimulated liver progenitor cells." (PMID 39125617, 2024). "The histopathological phenotype of modestly increased steatosis and inflammation (i.e., steatohepatitis) was manifested in the Nrf1, but not Nrf2-deficient livers, and their combined deficiency caused a significant phenotype of steatohepatitis, resulting in the hepatocyte ballooning." (PMID 40703332, 2025). "Both the mRNA and protein expression levels of PGC-1α, NRF1, NRF2, and mtTFA in steatosis cells were down-regulated compared with those in the control cells and the steatosis LO2 cells administered taurine." (PMID 37373507, 2023). "Physiologic Nrf1 delays MASLD progression, Nrf2 induction alleviates MASH, and combined enhancement synergistically protects against steatosis and may facilitate liver repair." (PMID 39125617, 2024). "Furthermore, liver-specific overexpression of NRF1 dramatically increased proteasome abundance and ameliorated MASH, as evidenced by the alleviation of steatosis, mitigation of liver damage, decreased infiltration of inflammatory cells and inhibition of hepatic fibrosis." (PMID 41545342, 2026). "Thus, in line with our results, decreased expression of the mitochondrial biogenesis transcription factors PGC1α and NRF1, and decreased expression of respiratory Complex I and V subunits NDUFS8 and ATP5G1 in the HepG2 cell model of steatosis have been reported." (PMID 29949946, 2018).
Cerebral ischemia (10 papers, 2012 to 2025). Restriction of arterial blood supply to the brain associated with insufficient oxygenation to support the metabolic requirements of the tissue. "Collectively, our findings indicated that the neuroprotective effect of CAT against cerebral ischemia was associated with the inhibition of autophagy via the NRF1/KAT2A/METTL3/Beclin-1 axis." (PMID 38773376, 2024). "As a result, the present study revealed that CAT, the main active component of Rehmannia, protected against cerebral ischemia in vivo and in vitro by inhibiting neuronal injury and autophagy via the NRF1/KAT2A/METTL3/Beclin-1 axis." (PMID 38773376, 2024). "It has been reported that CAT played a protective role in cerebral ischemia by upregulaing NRF1 expression." (PMID 38773376, 2024). "Tannic acid significantly reduced oxidative stress, as indicated by the decreased levels of ROS and MDA, whereas increased SOD and nuclear respiratory factor-1 (NRF-1) levels in brain tissues of rats with brain ischemia." (PMID 35215469, 2022). "NRF1 plays a vital role in mitochondrial biogenesis and redox signaling during cerebral ischemia." (PMID 40299522, 2025). "NRF1 is identified as a protective factor in cerebral ischemia progression." (PMID 38773376, 2024). "Moreover, CAT has been reported to upregulate NRF1 expression, and overexpressed NRF1 played a protective role in ischemic encephalopathy." (PMID 38773376, 2024). "Interestingly, selenium pretreatment increased the protein levels of PGC-1α and NRF1 at basal level and increased further after cerebral ischemia and recirculation as compared to respective control." (PMID 22776356, 2012). "It was reported that SA improved the activity of superoxide dismutase (SOD) and the levels of nuclear respiratory factor-1 (NRF1) and inhibited the levels of MDA in rats with cerebral ischemia injury." (PMID 38399751, 2024). "Molecularly, the main regulator of mitochondrial biogenesis PGC-1α improved mitochondrial function by activating its downstream genes NRF1 and TFAM, thereby remitting cerebral ischemia–reperfusion injury." (PMID 38773376, 2024). "CAT activated the NRF1/KAT2A/METTL3 axis and downregulated Beclin-1 expression, thus relieving neuronal injury and excessive autophagy after cerebral ischemia." (PMID 38773376, 2024). "It has been documented that CAT can increase the expression of nuclear respiratory factor 1 (NRF1), and elevated NRF1 can improve cognitive performance and play a protective role in rat models of ischemic encephalopathy." (PMID 38773376, 2024). "Compared with the global cerebral ischemia group, the sevoflurane post-conditioning group had much higher gene and protein expression levels of PGC-1α, NRF-1, and TFAM in the hippocampus after reperfusion." (PMID 27965539, 2016). "Overall, NRF1 activated METTL3 transcription via KAT2A, which may play a protective role in cerebral ischemia." (PMID 38773376, 2024). "Moreover, bioinformatics data and experimental results implied that NRF1 activated METTL3 transcription via KAT2A, which assumed a neuroprotective role in cerebral ischemia." (PMID 38773376, 2024). "On this basis, we conjectured that NRF1 may activate METTL3 transcription by promoting KAT2A transcription and increasing H3K27 acetylation level in METTL3 promoter region, thus playing a protective role in cerebral ischemia." (PMID 38773376, 2024). "Accordingly, we analyzed the mechanism of CAT in cerebral ischemic via the NRF1/KAT2A/METTL3/Beclin-1 axis with the focus on neuronal injury and autophagy, aiming to offer a theoretical basis for the development of CAT as neuroprotective drugs for the prevention and treatment of cerebral ischemia." (PMID 38773376, 2024).
Parkinson disease (10 papers, 2016 to 2024). A progressive degenerative disorder of the central nervous system characterized by loss of dopamine producing neurons in the substantia nigra and the presence of Lewy bodies in the substantia nigra and locus coeruleus. "Intriguingly, given Fbxo7’s role in Parkinson’s disease, a site for nuclear respiratory factor 1 (NRF1) was also found in its promoter." (PMID 33774278, 2021). "Its role in mitochondrial processes is considered to be important in relation to its role in neurodegenerative diseases, and it has been shown that the targets of NRF1 include genes involved in neurodegenerative diseases like Parkinson’s disease and AD." (PMID 32327964, 2020). "It was revealed that Pbx1 provides a beneficial effect of protecting against oxidative stress by increasing Nfe2l1 (also called NRF1), and decreasing levels of both TFs were found in midbrain dopaminergic neurons of Parkinson's patients." (PMID 31584878, 2019). "For examples, NRF1 target genes- PARK2, PARK6 (PINK1), PARK7, PAELR (GPR37) are associated with Parkinson’s disease." (PMID 27983596, 2016). "In muscle, Nrf1 has been shown to be a direct PGC-1 target, the master regulator of mitochondrial biogenesis, whose dysfunction has been implicated in several neurodegenerative diseases, such as Parkinson’s disease." (PMID 30333037, 2018). "NRF1 promotes m6A modification and IGF2BP2‐dependent stability of GLRX mRNA by increasing the expression of METTL3 and leads to the increase of GLRX expression, thus alleviating motor dysfunction and dopamine neuron degeneration in Parkinson's disease mice." (PMID 37735974, 2024).
prostate carcinoma (10 papers, 2010 to 2025). A carcinoma that arises from epithelial cells of the prostate gland. "Aberrant NRF1 has been linked to tumorigenesis, as some key oncogenes are regulated by NRF1, including genes related to glioblastoma, breast tumorigenesis, bladder cancer, prostate cancer, liver hepatocellular carcinoma and EBV-associated gastric cancer." (PMID 38055835, 2024). "There is human sample set data showing that NRF1 mRNA levels are also downregulated in prostate carcinoma but they are upregulated in oesophageal squamous cell carcinoma." (PMID 31687076, 2019). "This review covers the possible roles of two ROS-induced transcription factors, Nrf1 and Nrf2, and the antioxidant proteins peroxiredoxin-1 (Prx-1) and Thioredoxin-1 (Txn-1) in modulating AR expression and signaling in aggressive prostate cancer (PCa) cells." (PMID 24281119, 2010). "OCT4, a TF that can form complexes with other TFs (e.g., forkhead box protein A1 (FOXA1), androgen receptor (AR), and nuclear respiratory factor 1 (NRF1)), promotes prostate cancer (PCa) progression through epigenetic alterations and acquires chemotherapy resistance." (PMID 40642070, 2025). "Further investigation must be carried out to delineate the role of Nrf1 in the response to hypoxia and ADT in prostate cancer." (PMID 24281119, 2010). "In AR-negative prostate cancer cells, OCT4 forms LLPS with Nuclear respiratory factor 1 (NRF1)." (PMID 35966880, 2022).
colorectal cancer (9 papers, 2017 to 2025). A primary or metastatic malignant neoplasm that affects the colon or rectum. "Upregulated NRF1 expression in colorectal cancer activates mitochondrial metabolism and biosynthesis, promoting the growth, invasion, and metastasis of tumor cells." (PMID 40686517, 2025). "Human colorectal cancer HCT116 cells were transfected with NRF1 siRNA following treatment with the proteasome inhibitor MG132." (PMID 37658135, 2023). "In addition, miR-15b-5p was downregulated by nuclear respiratory factor 1 (NRF1), a transcription factor enriched in colorectal cancer, which is promoted by the elevated levels of interleukin IL-17A." (PMID 38339019, 2024). "Together, these findings suggest that inhibition of Jerky, NRF1, or their physical interaction may provide promising therapeutic strategies for colorectal cancer." (PMID 28708826, 2017). "The role of IL‐17A in lung cancer treated with ICI is still not largely unknown, but a study showed that IL‐17A can increase the expression of PD‐L1 in colorectal cancer treated with anti‐PD‐1 therapy via p65/NRF1/miR‐15b‐5p and promotes the resistance of anti‐PD‐1 thearpy." (PMID 37062076, 2023).
non-alcoholic steatohepatitis (9 papers, 2011 to 2026). "Notably, previous studies have linked NRF1 inactivation to the development of nonalcoholic steatohepatitis, while YY1 upregulation has been associated with fatty liver diseases, whereas E2F4 was found to promote HCC proliferation." (PMID 37627157, 2023). "It has been demonstrated that Nrf1 knockout mice accumulate lipids in the liver and exhibit a phenotype that mimics human non-alcoholic steatohepatitis." (PMID 34439537, 2021). "For instance, studies of liver-specific and brain-specific Nrf1 knockout mice have elucidated Nrf1's importance in preventing non-alcoholic steatohepatitis and neurodegeneration, respectively." (PMID 23144760, 2012). "Interestingly, in mice liver-specific inactivation of Nrf1 results in non-alcoholic steatohepatitis and hepatic cancer." (PMID 21695230, 2011).
Hepatic steatosis (8 papers, 2016 to 2026). Steatosis is a term used to denote lipid accumulation within hepatocytes. "H&E staining of hepatic tissues revealed that NRF1 overexpression alleviated hepatic steatosis, hepatocyte ballooning and inflammatory cell infiltration, which are typical characteristics of MASH." (PMID 41545342, 2026). "Liver-specific overexpression of NRF1 in mice markedly ameliorated HFD-driven hepatic steatosis, liver injury and inflammation." (PMID 41545342, 2026). "Second, NRF1 and NRF2 were discovered to be complementary genes that modulated cholesterol-associated fatty liver disease progression." (PMID 41545342, 2026). "The results show that EMPA ameliorated MASLD by reducing hepatic steatosis and attenuating oxidative stress via NRF1." (PMID 40362294, 2025). "Furthermore, EMPA alleviated HFD-induced hepatic steatosis and oxidative stress; however, these effects were lost in Nrf1-knockdown mice." (PMID 40362294, 2025). "Knocking down Nrf1 exacerbated hepatic steatosis and increased TG levels." (PMID 40362294, 2025). "Hepatocyte Nrf1 and combined deficiency increased liver steatosis in control diet-fed but not HFFC diet-fed mice, and increased liver inflammation under both diet conditions." (PMID 39125617, 2024). "However, it was reported that the protein levels of PGC-1α decreased in mice with fatty liver followed by reduction of NRF1 and TFAM, the mRNA abundance of PGC-1α increased." (PMID 32230804, 2020). "Notably, DHA preferentially upregulated the expression of NRF1 in the pericentral zone compared to the intermediate and periportal zones, which coincided with the zone exhibiting the most significant amelioration of hepatic steatosis." (PMID 41545342, 2026). "In control diet fed mice, Nrf2 deficiency was nonconsequential, while Nrf1 and combined deficiency exacerbated the effect, as demonstrated by hepatic steatosis as well as significant or trending increases in hepatic triglyceride and expression of Ccl2, Ccnb1, Col1a1, Col3a1, Ihh, and Tnfrsf12a." (PMID 39125617, 2024). "Furthermore, compared with the control group, hepatic steatosis (fatty liver group) led to decreased mRNA abundance of RXRα, ACO, CPT1, CPT2, LCAD, Nrf1 and TFAM (p < 0.05 or p < 0.01)." (PMID 32230804, 2020).
ischemia (8 papers, 2012 to 2025). A hypoperfusion of the BLOOD through an organ or tissue caused by a PATHOLOGIC CONSTRICTION or obstruction of its BLOOD VESSELS, or an absence of BLOOD CIRCULATION. "From them all, the CCCTC-binding factor (CTCF), the glucocorticoid receptor (NR3C1), and the nuclear respiratory factor 1 (NRF1) were connected to nodes exhibiting opposite regulation at revascularization and post-conditioning versus ischemia." (PMID 35216205, 2022). "Treadmill training increased levels of PGC-1 and NRF-1 mRNA, indicating that exercise promotes rehabilitation after ischemia via regulation of mitochondrial biogenesis." (PMID 22408416, 2012). "A previous study reported that ischemia-induced NRF1 increases at 72 h after I-R injury." (PMID 24667167, 2014). "Expression of two genes critical for transcriptional regulation of mitochondrial biogenesis, peroxisome proliferator-activated receptor coactivator-1 (PGC-1) and nuclear respiratory factor-1 (NRF-1), were examined by RT-PCR after five days of exercise starting at 24 h after ischemia." (PMID 22408416, 2012). "Overall, NRF-1 may play a complex role in regulating RFC1 in ischemia." (PMID 37328777, 2023). "To determine NRF1 expression in macrophages during ischemia-reperfusion injury, we established a C57BL/6 J mouse model of acute kidney injury induced by ischemia and reperfusion injury." (PMID 40374603, 2025). "However, the K105R or/and K139R mutants of Nrf1 counteracted the impact of PTS in the OGD/R-induced microglial injury model, which indicates that PTS treatment might be a promising strategy for ischaemia stroke therapy." (PMID 39198723, 2024).